BMP4 (bone morphogenetic protein 4)
Diseases named in the same sentence as BMP4 in open-access papers (continued):
Sharing a sentence is not in itself a finding about the gene and the disease.
myeloma (11 papers, 2012 to 2023). "Many BMPs can induce growth arrest and apoptosis of myeloma cells in vitro and BMP4 gene therapy inhibited tumor growth in a multiple myeloma mouse model." (PMID 36717825, 2023). "BMP4 also induces growth arrest and apoptosis in multiple myeloma cell lines as well as in primary myeloma cells from patients." (PMID 35915750, 2022). "For example, in myeloma cells, BMP4 inhibits DNA synthesis depending on interleukin-6 by downregulating tyrosine phosphorylation of Stat3 induced by interleukin-6 and then inhibits tumor cell proliferation." (PMID 35401213, 2022). "Recently, AAV8 vectors were used to systemically overexpress BMP4 from the liver in a mouse model of multiple myeloma, in which humanized bone scaffolds were implanted subcutaneously." (PMID 32674264, 2020). "In this study we wanted to explore BMP4 gene therapy as a potential treatment for multiple myeloma in a human‐mouse model." (PMID 31956851, 2020). "When mature BMP4 was detectable in the circulation, myeloma cells were injected into the scaffolds and tumor growth was examined by weekly imaging." (PMID 31956851, 2020). "We therefore evaluated the effects of AAV‐based BMP4 gene therapy in a human‐mouse scaffold model of multiple myeloma." (PMID 31956851, 2020). "We therefore explored BMP4 gene therapy in a human‐mouse model of multiple myeloma where humanized bone scaffolds were implanted subcutaneously in RAG2−/− γC−/−mice." (PMID 31956851, 2020). "Bone morphogenetic protein 4 (BMP4) is important for both pre‐ and postnatal bone formation and induces growth arrest and apoptosis of myeloma cells." (PMID 31956851, 2020). "As soon as BMP4 overexpression became detectable in the blood, myeloma cells were injected into the scaffolds and myeloma growth was inhibited compared to control animals." (PMID 32674264, 2020). "First, MEG3 has been reported to promote osteogenic differentiation of MSCs from multiple myeloma patients by releasing sex-determining region Y box 2- (SOX2-) mediated transcriptional suppression of bone morphogenetic protein 4 (BMP4) promoter." (PMID 28951743, 2017). "BMP4‐treatment of myeloma patients could have the potential to reduce tumor growth and restore bone formation." (PMID 31956851, 2020). "In this study we wanted to clarify if BMP4 could have therapeutic potential in multiple myeloma patients, by preventing tumor growth and restoring bone homeostasis." (PMID 31956851, 2020). "Thus, we here show that BMP4 gene therapy inhibited myeloma growth in a relevant in vivo model." (PMID 31956851, 2020). "Moreover, BMP4 was shown to induce growth arrest and apoptosis in myeloma cells." (PMID 32674264, 2020). "In addition, HGF inhibits BMP-2-induced generation of osteoblasts in multiple myeloma, prompting the continued proliferation of MSCs and thus could promote chondroblast proliferation and cartilage formation in conjunction with BMP-4." (PMID 26098852, 2015). "These cells responded poorly to the ligands BMP2, BMP4 and BMP10, that normally would require ALK3 to signal in myeloma cells." (PMID 36717825, 2023). "Most surprisingly we identified here a switch in ligand specificity as BMP2, BMP4, and BMP10, ligands that usually signal via ALK3 in myeloma cells, gained the ability to signal via ALK2 in the presence of FK506." (PMID 36717825, 2023). "The BMP4 was biologically active, since addition of sera obtained from the AAV8‐BMP4‐treated mice to the murine myeloma cell line NS0, led to reduction in cell viability, e.g. ATP levels, and adding a BMP4‐neutralizing antibody restored viability." (PMID 31956851, 2020). "To delineate the effects of BMP4 overexpression on bone per se, without direct influence from cancer cells, we examined the unaffected, non‐myeloma femurs by μCT." (PMID 31956851, 2020). "Ligands that typically signal via ALK3 in myeloma cells, BMP2, BMP4, and BMP10, did not induce apoptosis in cells lacking ALK3." (PMID 36717825, 2023).
myeloma (continued). "When recombinant BMP4 was detectable in blood plasma (data not shown), fluorescently labeled KJON myeloma cells were injected directly into the scaffolds." (PMID 31956851, 2020). "BMP-6 and BMP-9 signals through the type 1 receptor ALK2 in myeloma cells, whereas BMP-2 and BMP-4 do not signal in cells that express ALK2, but lack ALK3 and ALK6, as is the case for the INA-6 myeloma cell line." (PMID 26047946, 2015). "Using myeloma cell lines as a model system, we show that activin A antagonizes BMP-6 or BMP-9-signaling through ACVR2A/ACVR2B/ALK2, but not BMP-2 or BMP-4-signaling through BMPR2/ALK3 or BMPR2/ALK6." (PMID 26047946, 2015). "The main finding reported here is that activin A, by sharing receptors with BMP-6 and BMP-9, but not BMP-2 and BMP-4, may inhibit BMP-6 and BMP-9-induced apoptosis in myeloma cells." (PMID 26047946, 2015).
cardiac hypertrophy (10 papers, 2012 to 2025). "BMP4 is linked to pathological cardiac hypertrophy through activation of proliferation pathways; thus, it may also contribute to compensatory renal growth." (PMID 33168884, 2020). "The importance of BMP4 signaling in the development of cardiac hypertrophy was demonstrated in studies showing that pressure overload‐induced left ventricular hypertrophy and cardiac ischemia–reperfusion injury were attenuated in BMP4‐deficient animals or when BMP inhibitors were used." (PMID 32319199, 2020). "We found that BMP4 also induced their apoptosis by modulating the levels of apoptosis regulatory proteins, which is in agreement with a previous study that BMP4 mediates cardiac hypertrophy, and apoptosis in experimentally pathological cardiac hypertrophy." (PMID 35915750, 2022). "With this regard, our results are in agreement with the previous findings showing higher BMP4 expression in pathological cardiac hypertrophy." (PMID 32319199, 2020). "BMP4 is expressed in pathological cardiac hypertrophy models and BMP4-mediated cardiomyocyte hypertrophy." (PMID 25591903, 2015). "Taken together, these results indicate that m6A modification may promotes KCNN2 and BMP4 mRNA stability when mice develop cardiac hypertrophy." (PMID 35953789, 2022). "Both KCNN2 and BMP4 have been confirmed to play essential roles in cardiac hypertrophy." (PMID 35953789, 2022). "This indicates that spontaneous physical exercise does not increase the risk of the progression of the BMP4–mediated pathological cardiac hypertrophy." (PMID 32319199, 2020). "This study shows that long‐lasting physical exercise does not increase the risk of the progression of the BMP4–mediated pathological cardiac hypertrophy." (PMID 32319199, 2020). "We have concluded that prolonged period of spontaneous physical exercise does not increase the risk of the progression of the BMP4‐mediated pathological cardiac hypertrophy and does not affect bone mineral status in the chronic heart failure mice." (PMID 32319199, 2020). "The expression of BMP4 is up-regulated in myocardial hypertrophy induced by pressure load and Ang II, the expression of BMP4 can induce cardiomyocyte hypertrophy, apoptosis, and myocardial fibrosis, and enhance the effect of myocardial hypertrophy induced by Ang II." (PMID 36311192, 2022). "Considering the role of BMP4 in the pathological cardiac hypertrophy our results might suggest that an improvement of cardiac function in chronic heart failure conditions might be BMP4‐dependent." (PMID 32319199, 2020). "Several studies about BMP4 in cardiovascular system have implied that BMP4 might be involved in pathological cardiac hypertrophy, for example, BMP4 stimulates ROS production through NADPH oxidases in endothelium, exaggerates cardiac ischemia-reperfusion injury by promoting cardiomyocytes apoptosis." (PMID 25591903, 2015). "Thus, they concluded that BMP4 expression increases only in the pathological (pressure‐overload or angiotensin infusion), but not physiological (physical training) cardiac hypertrophy." (PMID 32319199, 2020). "Unlike BMP4, GATA4, another transcription factor related to cardiac hypertrophy, was downregulated in both groups fed an HCD." (PMID 35347086, 2022). "Foxm1 deletion did not alter mRNA expression of genes critical for cardiac hypertrophy and fibrosis such as α-SMA, collagen 1α1, CaMKIIδ, TNFα, BMP4, MMP9, CXCR4 and Hey2." (PMID 23144938, 2012). "Interestingly, the level of BMP4, a member of the bone morphogenetic protein family and a mediator of cardiac hypertrophy, was elevated in the 5.5CG (consistent with the increased IVS-d and IVS-s values in the 5.5CG) but also in the 5.5CR, which did not feature cardiac hypertrophy." (PMID 35347086, 2022).
Hepatic steatosis (10 papers, 2019 to 2025). Steatosis is a term used to denote lipid accumulation within hepatocytes. "We next sought to delineate the mechanism underlying BMP4-inhibited hepatic steatosis." (PMID 31831718, 2019). "BMP4 suppresses markers of hepatic steatosis, inflammation, and liver injury by upregulating glutathione peroxidase 4 (GPX4), thereby reducing ferroptosis." (PMID 40243151, 2025). "BMP4 has been shown to inhibit HFD-induced hepatic steatosis in mice by regulating genes involved in lipid metabolism and mTORC1 signaling in hepatocytes." (PMID 40243151, 2025). "It was also displayed that BMP4 alleviates hepatic steatosis by increasing hepatic lipid turnover and inhibiting the mTORC1 signaling axis in hepatocytes." (PMID 39466591, 2024). "Previous studies have found that BMP4 alleviates hepatic steatosis, promotes hepatic glycogen accumulation, and reduces glucose levels." (PMID 35477568, 2022). "In summary, we demonstrated that exogenous BMP4 inhibited the hepatic steatosis and alleviated the development and progression of NAFLD in a mouse model." (PMID 31831718, 2019). "Here, we demonstrated that exogenous BMP4 inhibited the hepatic steatosis, lowered serum triglyceride (TG) and body weight, and alleviated the development and progression of NAFLD in a mouse model." (PMID 31831718, 2019). "Exogenous BMP4 inhibited hepatic steatosis, reduced serum triglyceride levels and body weight, and alleviated progression of NAFLD in vivo." (PMID 31831718, 2019). "BMP4 suppressed the markers of hepatic steatosis, liver inflammation, and liver injury." (PMID 35477568, 2022). "This study investigated whether GLP-1 receptor agonist improves fatty liver by influencing the expression of BMP4 in the liver and regulating BMP4-related signaling pathways." (PMID 33986800, 2021). "Collectively, these results strongly suggest that exogenous BMP4 may suppress hepatic steatosis and alleviate the development and progression of NAFLD by inhibiting mTORC1 signaling." (PMID 31831718, 2019). "Bone morphogenetic protein 4 (BMP4) plays an important role in adipogenesis and differentiation, as well as in hepatic steatosis and iron regulation." (PMID 35477568, 2022). "A recent study reported upregulated BMP4 expression in oleic acid (OA)-induced hepatic steatosis and in a mouse model of high-fat diet (HFD)-induced NAFLD, and BMP4 may alleviate hepatic steatosis." (PMID 35477568, 2022). "Exenatide could improve HFD-induced hepatic steatosis and enhance thermogenesis in BAT, which may be partly attributed to the inhibition of the BMP4-related signaling pathway." (PMID 33986800, 2021). "However, no study has focused on the study of BMP4 on NASH, which is the development of hepatic steatosis." (PMID 35477568, 2022).
leukemia (10 papers, 2014 to 2023). A malignant (clonal) hematologic disorder, involving hematopoietic stem cells and characterized by the presence of primitive or atypical myeloid or lymphoid cells in the bone marrow and the blood. "Acute myeloid leukemia (AML) patients who express high BMP-4 and BMPR1a have higher relapse risk due to enhanced leukemia stemness." (PMID 32318332, 2020). "Underlying mechanisms that govern the effects of leukemia cells on BMP4 genes in BM-MSCs are still unknown, although some ideas can be proposed." (PMID 24400095, 2014). "A study indicated that BMPR1B, Stat3, and BMP4-niche signaling pathways regulate leukemia remission." (PMID 37373155, 2023). "Concerning the possible leukemia-promoting effects, it has been shown that BMP4 overexpression in ALL cells potentiates their ability to induce immunosuppressive dendritic cells (DCs) and to polarize macrophages to an M2-like pro-tumoral phenotype." (PMID 33922612, 2021). "This was the first demonstration of a niche-driven AML leukemia cell reprogramming toward an SC-like phenotype, featuring BMP4 as a key stemness regulator." (PMID 35047500, 2021). "First, hematopoietic cells, including leukemia cells, like germline cells, express Sall4 and respond to stimulation by bone morphogenetic protein 4 (BMP-4)." (PMID 26701888, 2016). "The involvement of BMP4 in the altered behaviour of leukemia MSC is evidenced also by the responses observed to the different doses of the morphogen and to the blockade of the signaling pathway." (PMID 24400095, 2014). "Indeed, concomitantly to intrinsic SC alterations, an increase in soluble BMP2 and BMP4, compared to healthy individuals, was detected within the tumor microenvironment of leukemia and breast cancer." (PMID 35047500, 2021). "BMP4 decreases during late childhood/young adulthood and then increases again during physiological aging, as well as in pathological conditions including metabolic syndrome, leukemia or bone fractures." (PMID 32896271, 2020). "Although high doses of BMP4 reduce proliferation of some leukemia cell lines, the effects of BMP4 could be mainly mediated by the stroma components rather than directly on hematopoietic cells." (PMID 24400095, 2014). "We also analyzed the relevance of leukemia cells for BMP4 production by MSCs." (PMID 24400095, 2014). "Alteration of BMP receptor type 1b (BMPR1b) expression at the HSC surface is induced by the expression of BCR-ABL and these molecular changes led to altered responses of leukemia cells to BMP2 and BMP4 as compared to normal bone marrow cells." (PMID 35047500, 2021). "Future work could focus on the blockade of BMP4 secretion by ALL cells which could help, in those patients who relapse, to control leukaemia progression by counteracting the development of a pro-tumour immune microenvironment." (PMID 31337120, 2019). "Correlating these results with bone morphogenetic protein 4 (BMP4) production, a molecule demonstrated to affect MSC biology, we found higher production of BMP4 in ALL-MSCs derived from patients over the course of disease but not in those free of leukemia." (PMID 24400095, 2014). "In addition, co-culturing ALL-MSC with the REH leukemia cell line, but not CD34+ hematopoietic progenitors, powerfully enhanced BMP4 production, suggesting an intimate crosstalk among ALL-MSCs isolated from BM colonized by ALL cells that presumably also occurs in situ conditions." (PMID 24400095, 2014).
Hyperglycemia (9 papers, 2013 to 2024). An increased concentration of glucose in the blood. "Both Apoe–/– and Ins2Akita/+ mice have enhanced endothelial BMP4 expression in response to hyperglycemia and hyperlipidemia, respectively, which mimics the loss of BMP inhibition and allows an emergence of EndMTs and VC." (PMID 34079793, 2021). "Both BMP2 and BMP4 are upregulated in atherosclerotic lesions associated with oxidative stress, inflammation and hyperglycemia." (PMID 31561501, 2019). "OxLDL, mechanical stress, and estrogen all have an inductive effect on BMP2, whereas shear stress, hyperglycemia, hyperlipidemia, and oscillatory shear stress enhance BMP4." (PMID 34079793, 2021). "Experimental studies found that hyperglycaemia in early pregnancy affected regulatory gene expression in the embryo for genes, such as Bmp4, Msx1, and Pax3, leading to cardiac neural crest cell death and an increased risk of CHD." (PMID 33062711, 2020). "Under hyperglycemia, P. gingivalis infection initiates vascular calcification in human aortic SMCs by autocrine regulation of BMP4." (PMID 33334022, 2020). "Hyperglycemia and diabetes are strong activators of BMP signaling, and BMP2 and BMP4 are associated with atherogenesis in hyperglycemia." (PMID 31561501, 2019). "It is possible that the decrease in serum BMP-4 after bariatric surgery was mediated by amelioration of hyperglycemia in the remission group." (PMID 24170999, 2013). "Indeed, endothelial Bmp4 expression is highly responsive to hyperglycemia, hyperlipidemia, and inflammation, and is increased in obese humans where BMP4 correlates positively with adipocyte size." (PMID 38184275, 2024). "Moreover, hyperglycemia can accelerate CRC progression by activating BMP4 signaling." (PMID 38313367, 2024). "In addition, to the observed in vivo increase in BMP2 by hyperglycemia, treatment of HRECs with HG upregulated mRNA of BMP2 and BMP4 and their downstream effectors such as ALKs, SMADs, and TGFβ mimicking the effect of rhBMP2 treatment." (PMID 33584642, 2020).
Insulin resistance (9 papers, 2013 to 2026). Increased resistance towards insulin, that is, diminished effectiveness of insulin in reducing blood glucose levels. "Previous study has showed that serum BMP-4 levels are significantly positively associated with adiposity, insulin resistance." (PMID 28376799, 2017). "It is known that genetic mutations of BMP-4 may be associated with decreased bone density in postmenopausal women and reduced adipocyte glucose uptake, thus inducing insulin resistance." (PMID 38840172, 2024). "These metabolic improvements were accompanied by coordinated changes in circulating components of the Gremlin-1/BMP-4 axis, including reduced serum BMP-4 levels and associations between BMP-4, Gremlin-1, and insulin resistance." (PMID 41828727, 2026). "Secondary outcomes included changes in BMP4-related parameters, insulin resistance as assessed by HOMA-IR, and body weight gain." (PMID 41596576, 2026). "BMP4, which is closely related to BMP2 was recently found to be upregulated in the serum of two diabetic mouse models and was proposed to contribute to insulin resistance by inhibiting IRS-1 activation and insulin signaling." (PMID 29222456, 2017). "High glucose-induced insulin resistance (IR)-CRC cells and diabetic mice with metastasis model of CRC had increased BMP4 expression, activated BMP4-Smad1/5/8 pathway, and improved proliferative and metastatic ability mediated by epithelial-mesenchymal transition (EMT)." (PMID 37370018, 2023).
metabolic syndrome (9 papers, 2013 to 2023). A cluster of metabolic risk factors for CARDIOVASCULAR DISEASES and TYPE 2 DIABETES MELLITUS. "Recently, we showed that serum BMP-4 levels are associated with human adiposity, insulin resistance, and metabolic syndrome in nondiabetic subjects." (PMID 24170999, 2013).